XRCC3 (X-ray repair cross complementing 3)
Diseases named in the same sentence as XRCC3 in open-access papers (continued):
Sharing a sentence is not in itself a finding about the gene and the disease.
DNA repair deficiency (1 paper, 2019). "Based on the results presented, we suggest considering genetic testing for RAD51 and XRCC3 to identify those men who have DNA repair deficiency and who have not responded to standard treatment." (PMID 31186630, 2019).
Erythema (1 paper, 2011). Redness of the skin, caused by hyperemia of the capillaries in the lower layers of the skin. "The allelic variant wt of XRCC3 Thr241Met is associated with a lower rate of erythema (OR = 0.29; 95% CI, 0.05-1.29)." (PMID 21749698, 2011). "The presence of the polymorphic variant mut/het of XRCC1 Arg194Trp and wt of XRCC3 Thr241Met results significantly in the protection towards developing an erythema with lower odds (OR = 0.2; 95% CI: 0.04-0.78)." (PMID 21749698, 2011). "In addition, when identifying the low and high risk groups, according to the absence or presence of mut/het XRCC1 Arg194Trp or wt XRCC3 Thr241Met, the observed erythema in our cohort was 20% and 59%, respectively." (PMID 21749698, 2011). "In the present study, a correlation was also found between the absence of erythema and the presence of a mut/het of XRCC1 Arg194Trp or of the wt XRCC3 Thr241Met, indicating the protective role of these alleles." (PMID 21749698, 2011).
esophageal cancer (1 paper, 2013). A primary or metastatic malignant neoplasm involving the esophagus. "Our data demonstrate the strong association between XRCC3 Met241Met genotype and expressed risk of susceptibility to both cervical and esophageal cancer in Kazakhstan populations." (PMID 23675381, 2013). "On the contrary, analysis of the homozygote genotype XRCC3 Met241Met (OR = 7.40, p = 0.02) detected a strong linkage to the esophageal cancer progression." (PMID 23675381, 2013).
esophageal squamous cell carcinoma (1 paper, 2022). Esophageal squamous cell carcinoma (ESCC) is a type of esophageal carcinoma (EC) that can affect any part of the esophagus, but is usually located in the upper or middle third. "High expression of XRCC3 in esophageal squamous cell carcinoma (ESCC) is associated with chemoradiotherapy resistance and predicts poor survival in patients." (PMID 35996502, 2022).
head and neck squamous cell carcinoma (1 paper, 2016). A squamous cell carcinoma that arises from any of the following anatomic sites: lip and oral cavity, nasal cavity, paranasal sinuses, pharynx, larynx, and salivary glands. "Another homologous recombination gene, XRCC3, was identified to correlate with CTLA4 expression in all three cancer types but exceeded the cutoff for CD274 only in head and neck squamous cell carcinoma." (PMID 27683114, 2016).
heart failure (1 paper, 2022). Inability of the heart to pump blood at an adequate rate to meet tissue metabolic requirements. "RAD51 polymorphisms were associated with symptoms of heart failure according to NYHA class and the occurrence of a new primary tumor, while XRCC3 polymorphisms were associated with tumor differentiation and skin adverse events according to LENT-SOMA criteria." (PMID 36139526, 2022).
hyperlipidaemia (1 paper, 2019). "In addition, EHM inhibited hyperlipidaemia by restoring the expression of genes and proteins related to DNA repair and energy metabolism, and proteins such as Hdac2, Xrcc2, Xrcc3, Uhrf1, and Prkar2b were identified as molecular targets playing key roles in ameliorating hyperlipidaemia." (PMID 31545933, 2019).
medulloblastoma (1 paper, 2022). A malignant, invasive embryonal neoplasm arising from the cerebellum. "Genomic analysis showing XRCC3 alterations suggested radiotherapy as contributing factor to the progression of LFS-associated medulloblastoma, and demonstrated different mechanisms of APC inactivation in the FAP-associated tumors." (PMID 35978432, 2022).
nasopharyngeal carcinoma (1 paper, 2021). A carcinoma arising from the nasopharyngeal epithelium. "XRCC3 722 C>T allele has also been associated with an increased risk of radiation-induced late xerostomia in nasopharyngeal cancer patients." (PMID 34079756, 2021).
neutropenia (1 paper, 2017). A decrease in the number of neutrophils found in the blood. "In our hands, XRCC3 316AA and AG alleles yielded statistically significant results: the OR for all neutropenia grade was 1.52 (95% CI: 0.51–4.91) for GA alleles, and the OR for GG+GA was 2.61 (95% CI: 0.91–7.61) P = 0.03." (PMID 29163177, 2017). "Here, we evaluated additional SNPs on the candidate genes: CYP3A4*22, GSTP1, ERCC2, SLCO1B1, and ABCG2, but did not observe a significant relationship with neutropenia and neurotoxicity except for XRCC3 316A>G rs1799794 for GG+AG alleles (p = 0.03)." (PMID 29163177, 2017).
nicotine addiction (1 paper, 2015). "In addition, smokers with the XRCC3 Thr241or KLC3 Lys751 alleles presented more nicotine addiction measured by FTND and more years smoking." (PMID 26017978, 2015). "Attending our results, across SNPs, XRCC3 Thr241Met and KLC3 Lys751Gln polymorphisms could be related to nicotine addiction measured as smoking amount (PYS) or years smoking." (PMID 26017978, 2015).
preeclampsia (1 paper, 2014). Preeclampsia is a hypertensive disorder of pregnancy that is characterized by new-onset hypertension with proteinuria presenting after 20 weeks of gestation, and depending on mild or severe forms may initially present with severe headache, visual disturbances, and hyperreflexia. "In the present study we aimed to investigate the association between APEX1 Asp148Glu, XPD Lys751Gln, XRCC1 Arg399Gln and XRCC3 Thr241Met polymorphisms and the risk of preeclampsia in a Mexican population." (PMID 24619222, 2014).
pterygium (1 paper, 2021). A wedge-shaped fibrovascular lesion arising from the bulbar conjunctiva and extending to the cornea. "It was previously reported that genes involved in double-strand DNA break repair, RAD50, RAD51, XRCC2 and XRCC3, are differentially expressed in pterygium." (PMID 34769520, 2021).
sarcoma (1 paper, 2022). A usually aggressive malignant neoplasm of the soft tissue or bone. "BRCA1, RAD51D, and additionally XRCC2 were downregulated in the M6 high-grade sarcoma, whereas XRCC3 was highly overexpressed." (PMID 35978432, 2022).
Xeroderma pigmentosum complementation group D (1 paper, 2014). Xeroderma pigmentosum complementation group D (XPD) is a subtype of xeroderma pigmentosum (XP; see this term), a rare photodermatosis predisposing to skin cancers. "Among them, polymorphisms of X-ray repair cross complementing group 1 (XRCC1), X-ray repair cross complementing group 3 (XRCC3), and xeroderma pigmentosum complementation group D (XPD) have been studied extensively." (PMID 24955348, 2014). "The genetic polymorphisms of X-ray repair cross complementing group 1 (XRCC1), X-ray repair cross complementing group 3 (XRCC3), and xeroderma pigmentosum complementation group D (XPD) repair genes may lead to genetic instability and leukemogenesis." (PMID 24955348, 2014).
cancer (65 papers, 2003 to 2025). A tumor composed of atypical neoplastic, often pleomorphic cells that invade other tissues. "Many studies have been conducted examining the effect of various XRCC3 polymorphisms on susceptibility to cancer." (PMID 38892180, 2024). "Particularly, the Arg194Trp and Arg399Gln variants of XRCC1, the Arg188His variant of XRCC2, and the Thr241Met variant of XRCC3 have been studied for their associations with various types of cancer." (PMID 38983993, 2024). "Earlier studies have shown that the XRCC3 Thr241Met polymorphism has long been regarded as a risk factor for many cancers." (PMID 36761956, 2023). "Several studies have demonstrated that the Thr241Met SNP of XRCC3 is associated with susceptibility to various cancers, including lung, bladder, endometrial, and laryngeal cancers." (PMID 37679817, 2023). "XRCC3 possesses multiple SNPs, and certain XRCC3 SNPs have been inextricably linked to tumorigenesis, cancer progression, and susceptibility to treatment." (PMID 37679817, 2023). "Regarding polymorphism in XRCC3 T241M, a significantly increased cancer risk was only observed in the allelic genetic model (OR=1.05, 95% CI= 1.00–1.11, P=0.04)." (PMID 36761956, 2023). "XRCC3 polymorphisms have been extensively tested for their association with radiotoxicities in a variety of cancers." (PMID 34079756, 2021). "XRCC3 rs1799794 increased cancer risk in the dominant model and heterozygous model (GG + AG vs. AA: odds ratio [OR] = 1.04, 95% confidence interval [CI] = 1.00–1.08, P = 0.051; AG vs. AA: OR = 1.05, 95% CI = 1.00–1.01, P = 0.015)." (PMID 33931047, 2021). "Variants of XRCC3 have been shown to be positively associated with late radiation-induced toxicity and elevated cancer risk." (PMID 34079756, 2021). "Taken all together, the hereby suggested cancer type- and population-specific association between 94Arg/His SNP in Xrcc3 and cancer risk needs to be further verified." (PMID 31905201, 2020). "In the case of Xrcc3, rs861539 (c.722C>T; 241Thr/Met) in exon 8 is the most frequently tested SNP with respect to cancer risk." (PMID 31905201, 2020). "The very few studies analyzing possible cancer risk-modifying effects of Rad51 and/or Xrcc3 haplotypes are, unfortunately, related to different type of cancers." (PMID 31905201, 2020). "Similar to XRCC1 and XRCC2, XRCC3 has been researched widely in the correlation between gene polymorphisms and the risk of cancer." (PMID 32258128, 2020). "It was revealed that there is a relationship between rs1799796 polymorphism in XRCC3 and the age of patients over 71 years (OR = 1.916, p = 0.033) and Gleason score of cancer equal to or higher than 7 (OR = 2.373, p = 0.012)." (PMID 31186630, 2019). "XRCC3 participates in HR to maintain chromosome stability and repair DNA damage and is therefore a highly suspected candidate gene for cancer susceptibility." (PMID 31374908, 2019). "XRCC2 Arg188His and XRCC3 Thr241Met polymorphisms were selected for their documented participation in the pathogenesis of cancers." (PMID 30712190, 2019). "RAD51B and XRCC3 polymorphisms have been identified as a risk factor for prostate, ovarian, breast, head and neck and other cancer types." (PMID 27683114, 2016). "The XRCC3 Thr241Met polymorphism has been investigated in various types of cancer and the findings have been varied." (PMID 25013509, 2014). "The XRCC3 Thr241Met polymorphism has been investigated in various types of cancer and the results are mixed." (PMID 25013509, 2014). "The XRCC3 gene is located in human chromosomes 14q32.3 and various polymorphisms in this gene have been identified with susceptibility to cancers such as Thr241Met (C18067T, rs861539), 5-UTR (A4541G rs1799794) and IVERSUS 5–14 (A17893G, rs1799796)." (PMID 24454720, 2014). "XRCC3 polymorphism was associated with the risks of many cancers, such as lung cancer, breast cancer, and head and neck cancer." (PMID 25006581, 2014).
cancer (continued). "This phenomenon indicates that the XRCC3 C18067T polymorphism exerts different effect on various types of cancers." (PMID 24454720, 2014). "Different results derived from previous meta-analysis which focused on relationship between XRCC3 Thr241Met polymorphism with cancers risk." (PMID 24454720, 2014). "Published data on the relationship of XRCC3 Trp241Met polymorphism with cancer risk are inconsistent." (PMID 23675381, 2013). "Three of these SNPs (CDKN1A-S31R, OGG1-S326C, and XRCC3-T241M) have already found to be associated with altered cancer risk." (PMID 16111488, 2005). "XRCC3 polymorphisms influence human cancer susceptibility by altering DNA repair efficiency." (PMID 35860595, 2022). "Our study shows that XRCC3 rs1799794 is irrelevant to cancer risk." (PMID 33931047, 2021). "The presence of the rs1799796 polymorphism in the intron region of the XRCC3 gene, if reduces gene expression, may interfere with DNA repair and contribute to the abundance of mutations and cancer risk." (PMID 31350979, 2019). "Several other studies and meta-analyses have confirmed an association between the XRCC3 Thr241Met polymorphism and it is suggested that this may be involved in modifying the risk of cancer." (PMID 26881229, 2016). "Based on a similar hypothesis of influencing radiotoxicity, the association of XRCC3 polymorphisms with cancer risk has also been extensively evaluated." (PMID 26091483, 2015). "XRCC3 participates in repair DNA-double strand break via homologous recombination, the polymorphism of XRCC3 Thr241Met has been indicated to be involved in the development of some cancers." (PMID 26017978, 2015). "Therefore, it is believed that the XRCC3 (241Met) variant is involved in susceptibility to cancer." (PMID 31350979, 2019). "XRCC3 plays a critical role in maintaining genomic integrity by repairing radiation-induced DNA double-strand breaks, and the XRCC3 polymorphism may affect the DNA repair capacity of its encoded protein, thus, contributes to the development of cancers." (PMID 24254304, 2014). "Similarly, interactions between XPC/XRCC3 and XPD/XRCC3 were observed, suggesting that coordination between both repair systems might contribute to the individual susceptibility to develop cancer." (PMID 17705814, 2007). "Of the eight HRR genes examined, the median methylation observed at the promoter regions of RAD51D and XRCC3 was ≤25% in all samples across all cancer types assessed, suggesting absence of promoter methylation for these two genes." (PMID 39055334, 2024). "In the TCGA PanCancer Atlas, homozygous deletions of XRCC3 were present in different types of cancers, with a low frequency (between 0.2 and 2.8%)." (PMID 37029129, 2023). "The mutation sites that have been studied more about the relationship between XRCC3 gene and cancer are rs861539, rs1799794 and rs1799796." (PMID 33931047, 2021). "The five classical RAD51 paralogs [RAD51B, RAD51C, RAD51D, XRCC2 and XRCC3] are important components of the homologous recombination pathway that preserves genomic integrity and protects against cancer." (PMID 31584931, 2019). "Associations between XRCC1, XRCC3, and ERCC2 gene polymorphism and prognosis have been investigated in several cancers." (PMID 31281357, 2019).
cancer (continued). "Studies in humans and mice with XRCC3 gene disruption confirm that these responses are likely to contribute to cancer induction and/or progression." (PMID 26881229, 2016). "The polymorphisms of the XRCC2 and XRCC3 were investigated by PCR–RFLP in 70 patients with TNBC and 70 age- and sex-matched non-cancer controls." (PMID 24728564, 2015). "There are many opinions about influence of XRCC1 (X-ray repair complementing defective repair in Chinese hamster cells 1) and XRCC3 (X-ray repair complementing defective repair in Chinese hamster cells 3) genes on different cancer types." (PMID 23675381, 2013). "Moreover, interaction dendrogram placed XPG rs17655 and family history of cancer in first‐degree relatives on the same branch, but XRCC3 rs861539 on another branch." (PMID 35691022, 2023). "Studies on the XRCC3 rs1799794 polymorphism show that this polymorphism is involved in a variety of cancers, but its specific relationships or effects are not consistent." (PMID 33931047, 2021). "But the most remarkable pro-cancer RAD52 phenotype is seen in cancer cells deficient in any of the following DNA repair proteins: BRCA1, BRCA2, PALB2, XAB2 or RAD51 paralogs: RAD51B, RAD51C, RAD51D, XRCC2 and XRCC3." (PMID 34887904, 2021). "An uncommon SNP in XRCC3 is related to cancer in patients of altering radiosensitivity." (PMID 29163177, 2017). "We identified genes from the homologous recombination pathway in the gene lists and cross-validation of all three candidate gene sets revealed striking overlaps between the different cancer types with several genes including XRCC3 and RAD51B as potential candidates for further investigation." (PMID 27683114, 2016). "The next protein XRCC3 acts as DNA repair genes and its function is in the maintenance of integrity of the genetic material, and hence its dysfunction plays critical roles in cancer development." (PMID 26308848, 2015). "XRCC2 and XRCC3 genes involved in homologous recombination repair (HRR) of DNA and in the maintenance of the genome integrity play a crucial role in protecting against mutations that lead to cancer." (PMID 24728564, 2015). "The three‐factors model consisted of XRCC3 rs861539, XPG rs17655 and family history of cancer in first‐degree relatives and it was the strongest and best model with a CVC of 10/10 and the highest testing accuracy of 71.08%." (PMID 35691022, 2023). "In contrast, RAD51B, XRCC3 and SPRTN were differentially methylated and also clustered closely together in all three cancer types." (PMID 27683114, 2016). "Finally, to estimate the prevalence of XRCC3 and ORC1 alterations in cancer, we queried the cBioPortal database." (PMID 37029129, 2023). "Compared with the best of one‐or‐three factor models, the best of the three‐factor model consisting of XRCC3 rs861539, XPG rs17655 and family history of cancer in first‐degree relatives had improved testing accuracy and CVC, and it was thought to be the fitted model." (PMID 35691022, 2023). "XRCC2 and XRCC3 proteins are structurally and functionally related to RAD51, which plays an important role in the homologous recombination, the process being frequently involved in cancer transformation." (PMID 24728564, 2015).
cancer (continued). "Variations in the XRCC3 gene might lead to altered protein structure or function which may change DSBR efficiency and result in cancer." (PMID 24454720, 2014). "Consistently with the changes in the invasive behaviour of the cells, we found that increased expression of XRCC3 resulted in increased activity of MMP-9, a gelatinase involved in the extracellular matrix (ECM) degradation that is thought to play an important role in cancer metastasis." (PMID 21283680, 2011).